ARHGEF40 (Rho guanine nucleotide exchange factor 40)
Description:
Acts as a guanine nucleotide exchange factor (GEF) for RHOA and RHOC. Promotes actin stress fiber formation, force-induced stress fiber reinforcement and organization of KRT8/KRT18 networks via activation of RHOA/ROCK signaling, which is mediated by N-terminus KRT18 binding. Regulates the formation or maintenance of properly elongated morphology of epithelial tubules, via mediation of the organization and orientation of KRT18 filaments (By similarity). Promotes RHOA-dependent, cell-cell contact mediated reorientation of endothelial cells and their actin stress fibers in response to mechanotransduction. Positively regulates hemidesmosome formation via acting as a linker protein that anchors keratin filaments to hemidesmosomes. Also required for JUP localization at cell-cell adhesion junctions.
Synonyms: SOLO; FLJ10357
Tractability: Antibody: its Gene Ontology location is reachable by antibodies, with high confidence; the Human Protein Atlas places it where antibodies can reach. PROTAC: ubiquitination databases record sites on it; its protein half-life has been measured.
Gene: Protein-coding gene on chromosome 14 (21,069,647 to 21,090,248, forward strand). Ensembl gene ENSG00000165801.
Subcellular location: Cytoplasm; Cytoplasm, cytoskeleton; Cell junction, hemidesmosome; Cell junction
Subcellular location (Human Protein Atlas): Cytosol; Plasma membrane
Pathways (Reactome):
Signal Transduction: G alpha (12/13) signalling events; NRAGE signals death through JNK; RHOA GTPase cycle; RHOC GTPase cycle
Gene Ontology:
Molecular function: guanyl-nucleotide exchange factor activity
Biological process: axon guidance; regulation of small GTPase mediated signal transduction
Cellular component: anchoring junction; cytoplasm; cytosol; extrinsic component of membrane; plasma membrane; cytoskeleton; hemidesmosome
Genetic constraint (gnomAD): Loss-of-function variants: 98 observed, 160.6 expected, observed/expected ratio (o/e) 0.61, 90% interval 0.52 to 0.72. The upper end of that interval is the gene's LOEUF score, 0.72, which puts it in group 2 of 6, group 1 being the genes least tolerant of losing a copy. Missense variants: 1,815 observed, 1,970.3 expected, observed/expected ratio (o/e) 0.92, 90% interval 0.88 to 0.96. Synonymous variants: 792 observed, 812.18 expected, observed/expected ratio (o/e) 0.98, 90% interval 0.92 to 1.03.
Homologues: Orthologues: chimpanzee ARHGEF40 (99% identical), macaque ARHGEF40 (96% identical), rabbit ARHGEF40 (90% identical), dog ARHGEF40 (88% identical), guinea pig ARHGEF40 (88% identical), pig ARHGEF40 (87% identical), mouse Arhgef40 (86% identical), rat Arhgef40 (86% identical), tropical clawed frog arhgef40 (21% identical). Paralogues in human: PLEKHG4B (27% identical), PLEKHG4 (22% identical), KIAA1755 (18% identical), TRIO (17% identical), KALRN (17% identical), MCF2L (13% identical), TIAM1 (12% identical), MCF2 (11% identical), TIAM2 (10% identical), MCF2L2 (10% identical), SPATA13 (8% identical), ARHGEF7 (8% identical), and 10 more.
Diseases named in the same sentence as ARHGEF40 in open-access papers:
ARHGEF40 is named in the same sentence as 6 diseases in open-access papers, as found by Europe PMC text mining. Sharing a sentence is not in itself a finding about the gene and the disease. The quoted sentences say what the papers report.
breast carcinoma (1 paper, 2025). "To explore the potential association between the RhoGEF Solo and EMT, we analyzed ARHGEF40/Solo gene expression in a TCGA breast cancer dataset." (PMID 40502686, 2025).
cutaneous melanoma (1 paper, 2020). A primary melanoma arising from atypical melanocytes in the skin. "Indeed, ARHGEF40 has a significantly higher expression in cutaneous melanoma samples as compared to normal skin samples, although it has no significant relation with overall or disease-free survival." (PMID 32276436, 2020). "In summary, we have identified three novel mutations in CDH23, ARHGEF40, and BRD9 genes, which could confer cutaneous melanoma susceptibility." (PMID 32276436, 2020).
hearing loss (1 paper, 2020). "Similar to ARHGEF40 and BRD9, the function of CDH23 has not been established hitherto in spite of being implicated in Usher syndrome type ID and non-syndromic hearing loss." (PMID 32276436, 2020).
melanoma (1 paper, 2020). A malignant, usually aggressive tumor composed of atypical, neoplastic melanocytes. "Interestingly, according to our Gene Ontology data, ARHGEF40 is particularly associated with skin and epidermal development, indicating that an ARHGEF40 mutation could have a relevant impact on melanoma." (PMID 32276436, 2020). "Therefore, ARHGEF40 could also be associated with melanoma initiation." (PMID 32276436, 2020). "Altogether, these results suggested that CDH23, ARHGEF40, and BRD9 genes could be also important for sporadic melanoma and consequently, a mutation in these genes could be pivotal in this disease." (PMID 32276436, 2020). "ARHGEF40 and BRD9 were mutated in 18 of 448 melanoma patients (4%)." (PMID 32276436, 2020). "Since CDH23, ARHGEF40, and BRD9 function is unclear, the impact of rare variants in these genes in melanoma context is unknown." (PMID 32276436, 2020). "Contrarily, ARHGEF40 had a significantly higher expression in SKCM samples when compared to normal skin samples, although its expression did not appear to correlate with melanoma stages or either overall or disease-free survival (p = 0.26 and p = 0.34)." (PMID 32276436, 2020).
cancer (1 paper, 2020). A tumor composed of atypical neoplastic, often pleomorphic cells that invade other tissues. "Therefore, these splicing alterations could also have an important impact on ARHGEF40 function, consequently influencing the activation of Rho GTPases, which might result in numerous disorders, including cancer." (PMID 32276436, 2020).
ARHGEF40 also shares sentences with these, for which no sentence is quoted: tumours (1 paper).